IL22 (interleukin 22)
Diseases named in the same sentence as IL22 in open-access papers (continued):
Sharing a sentence is not in itself a finding about the gene and the disease.
psoriasis (continued). "Immunopathological role of IL-22 has been studied in rheumatoid arthritis (RA) and psoriasis." (PMID 22417743, 2012). "IL-22 also mediates keratinocyte proliferation and epidermal hyperplasia and is thought to play a central role in wound healing as well as in inflammatory diseases such as psoriasis." (PMID 23226194, 2012). "Moreover systemic as well as intra-articular anti-TNF therapy showed reduction of increased IL-22 level in serum and synovial fluid of psoriasis and PsA patients respectively." (PMID 22417743, 2012). "Several reports suggest that IL-22, a relatively new Th17 cytokine plays a critical role in the inflammation and proliferation cascade of various autoimmune diseases like rheumatoid arthritis and psoriasis." (PMID 22417743, 2012). "This evidence strongly suggests that IL-22 plays a critical role in the pathogenesis of psoriasis." (PMID 22808266, 2012). "The critical role of CCR6 in psoriasiform inflammation was well documented by the observation of expression of CCR6 and CCL20 in psoriatic lesions and by the finding that both IL-17A- and IL-22-producing cells isolated from lesional skin of patients with psoriasis displayed CCR6." (PMID 21311769, 2011). "IL-17F and IL-22 are other cytokines typically produced by Th17 cells and may also play a role in the induction of psoriasis." (PMID 21124836, 2010). "Moreover, patients with active disease exhibited significantly higher levels of IL-17A, IL-23, and IL-22 than those with stable psoriasis, suggesting that these cytokines might play an important role in disease exacerbation." (PMID 40699767, 2025). "Additionally, IL-6 and IL-22 levels may serve as reliable biomarkers for monitoring treatment efficacy in psoriasis patients." (PMID 40699767, 2025). "Importantly, the field lacks much needed studies that use direct measures of brain inflammation in comorbid patients and appropriate controls, in conjunction with a larger array of serum markers, starting with cytokines targeted by biologics effective for psoriasis (such as IL-17, IL-22, IL-23)." (PMID 39959848, 2025). "Therefore, the factors, including IL-17A, IL-22, IL-1β, NLRC4, MEFV, and CASP5, detected by ocular surface test in our case should be verified for their usefulness as biomarkers for psoriasis-associated conjunctivitis in clinical studies involving a large number of cases." (PMID 40861543, 2025). "The psoriasis-like phenotype in the mice could be relieved by reducing bacterial load on the skin after applying topical antibiotics, along with the decrease of IL-17 and IL-22 production." (PMID 38347543, 2024). "The active ingredients of the three tea alcoholic extracts could modulate multiple signaling pathways through a variety of target proteins such as TNF-α, IL-17, FLG, Cytokeratin 17, IL-23, STAT3, FLG, IFN-γ, IL-22, etc., and thus attenuate or inhibit psoriasis." (PMID 38542915, 2024). "It balances IL-22’s main function in wound healing and in maintaining tissue homeostasis, it may reduce the tumor-promoting activity of IL-22 in hepatocellular carcinoma and may block IL-22 involvement in liver cirrhosis, chronic inflammation, psoriasis, and arthritis (Mühl & Bachmann, 2019)." (PMID 39769266, 2024). "In psoriasis, the long-standing proof for the use of baicalin alternative medicine was established via in vivo studies, where common symptoms such as epidermal thickening, erythema, and desquamation backed with IL-17A, IL-22, and IL-23 level were significantly reduced after treatment." (PMID 37371141, 2023). "This may indicate that IL-22 plays a protective effect against psoriasis." (PMID 38008779, 2023). "However, the dominant immune response in psoriasis is T helper 17 (Th17), whose characteristic cytokines are interleukin 17A (IL-17A), interleukin 17F (IL-17F), interleukin 21 (IL-21), interleukin 22 (IL-22), interleukin 29 (IL-29), interleukin 8 (CXCL-8), and tumor necrosis factor α (TNF-α)." (PMID 38001807, 2023).
psoriasis (continued). "Inhibiting the LPS-induced NF-κB pathway allows Kaempferia to prevent keratinocytes and macrophages from producing the pro-inflammatory factors TNF-α, IL-1, IL-6, IL-17, IL-22, and IL-23, indicating that this plant may be a promising candidate for the creation of anti-psoriasis medications." (PMID 37828492, 2023). "Besides, these discordant expressions at different sites put forward a hypothesis that differential IL-22 expression might result in diverse local manifestations of psoriasis." (PMID 35911703, 2022). "Both studies indicated that pediatric psoriasis patients might benefit from anti-IL-22 therapy." (PMID 35911703, 2022). "However, IL‐22 production was significantly higher in T cells derived from patients with psoriasis." (PMID 34913478, 2022). "On the other hand, Chen has shown that K23/IL-22+/+ and K23/IL-22−/− mice are not different and hypothesized that IL-22 deficiency is not required for psoriasis development, although IL-22 aggravates psoriatic arthritis in K23 mice." (PMID 35911703, 2022). "Besides, differential IL-22 expression at different sites might result in diverse local manifestations of psoriasis." (PMID 35911703, 2022). "Furthermore, miR-20a-3p and miR-330 are two IL-22 responsive microRNAs identified in psoriasis." (PMID 35075118, 2022). "Thus, combined therapies of anti-TNF-α (or anti-IL-23/IL-17) and anti-IL-22 intervention might be effective in anti-TNF-α (or anti-IL-23/IL-17)-resistant psoriasis individuals." (PMID 35911703, 2022). "Hence, considering the miR-21-3p/IL-22 axis could open a novel therapeutic track for the treatment of psoriasis." (PMID 34685526, 2021). "However, the loss of IL-36R signaling successfully counteracts and protects against the development of imiquimod-induced psoriasis compared to deletions of the IL-23/IL-17/IL-22 axis, indicating that IL-36 activity should be early in the cascade of psoriasis initiation." (PMID 34884834, 2021). "Inhibition of IL-22 by neutralization antibodies has been shown to reduce the expression of chemotactic factors, decrease antimicrobial and hyperproliferative responses of keratinocytes, and prevent the development of imiquimod-induced psoriasis from skin inflammation." (PMID 34295334, 2021). "Steatohepatitis promotes the progression of psoriasis in patients with NASH, and obesity exaggerates the severity of psoriasiform dermatitis caused by the Toll-like receptor 7 (TLR-7) agonist imiquimod (IMQ) by promoting IL-17A and IL-22 secretion and IL-1β overexpression in HFD-fed mice." (PMID 34944732, 2021). "Specifically, CD8 T-cells; CD4+ Th17 cells, responsible for producing IL-17 and IL-22; type 3 innate lymphoid cells, responsible for producing IL-17 and IL-22; and γδ T cells, responsible for producing IL-17 and TNF- α, are implicated in the pathogenesis of psoriasis." (PMID 34884596, 2021). "IL-22 stimulation promoted cell proliferation, migration and invasion of HaCaT cells, and these effects were largely attenuated by the silencing of circ_0061012, demonstrated that IL-22 promoted psoriasis progression partly through enhancing circ_0061012 expression." (PMID 33393621, 2021). "Of note, single-cell RNA sequencing and fate-mapping analysis on ILCs in the IL-23-induced mouse model of psoriasis showed that a group of quiescent ILCs could become activated ILC2s and could be further converted into IL-17- and IL-22-producing ILC3-like cells upon IL-23 stimulation." (PMID 34831296, 2021). "Additionally, several cytokines, such as tumor necrosis factor (TNF)-α, interleukin (IL)-1β, IL-12, IL-17A, IL-22, and IL-23, upregulate the production of reactive oxygen species and the hyperproliferative keratinocyte state seen in psoriasis, and are shown to play a role in some malignancies." (PMID 34685480, 2021). "Thus, we speculated that IL-22/IL-22R1 might be involved in the proliferation of epidermis in psoriasis." (PMID 32632545, 2020).
psoriasis (continued). "The pathogenesis of psoriasis seems to be driven by the interaction between innate immune cells, adaptive immune cells and keratinocytes, in a process mediated by cytokines (including interleukins (IL)-6, IL-17 and IL-22, interferon and tumor necrosis factor) and other signaling molecules." (PMID 32224981, 2020). "IL22, up-regulated in lesional skins of patients with psoriasis, could bind to the receptor in keratinocytes and promote the cell proliferation, thus is critical for the pathogenesis of psoriasis." (PMID 32650835, 2020). "An increase in the number of epidermal IL-17 and IL-22—producing skin-resident T CCR6 + cells—may be a genetically predisposed reaction to microbial stimulation in never-lesional skin in patients with psoriasis." (PMID 31963581, 2020). "Furthermore, we found a positive correlation with the ratio of IL-22/IL-22BP and Bcl-xL/Bax, suggesting that IL-22 might contribute to anti-apoptosis in psoriasis." (PMID 32632545, 2020). "However, the function of IL-22 in regulating apoptosis in psoriasis remains poorly understood." (PMID 32632545, 2020). "On the other hand, enhancement of IL-22BPi2 and IL-22BPi3 production may be indicated to control the deleterious actions of IL-22 in psoriasis and intestinal tumorigenesis, where IL-22BP prevents long-lasting proliferative actions of IL-22 on malignant epithelial cells." (PMID 31108847, 2019). "In a Th17-mediated psoriasis mouse model, an anti-IL-22 antibody attenuated symptoms and reduced expression of IL-36, whereas injection of rIL-22 had the opposite effects, suggesting that IL-22 can synergize with the proinflammatory effects induced by IL-36 procytokines." (PMID 31387327, 2019). "In conclusion, IL-22 may collaborate with other soluble factors and cells together forming inflammatory circuits that otherwise exist as constitutive or inducible pathways in normal skin and become pathologically amplificated in psoriasis." (PMID 30291393, 2019). "Among the most striking effects of IL-22 are upregulation of the expression of genes responsible for antimicrobial defense, cellular differentiation, and mobility in keratinocytes implicating a possible important role in inflammatory diseases with marked epidermal acanthosis, such as psoriasis." (PMID 30291393, 2019). "Although many immune diseases including psoriasis or atopic dermatitis have been traditionally classified as Th1/Th2 biphasic disorders, there is a growing evidence supporting a rather systemic activation of other multiple Th-cell subsets, such as Th17 cells producing IL-17 and IL-22." (PMID 31649677, 2019). "Other proinflammatory factors released by pathogenic Th17 cells, such as IL-22, TNF-α, and granulocyte-macrophage colony-stimulating factor (GM-CSF), stimulate keratinocytes to release chemokines, further sustaining the inflammatory cycle to promote the development of psoriasis." (PMID 29899748, 2018). "Although the absence of GR and MR in keratinocytes did not cause spontaneous psoriasis per se, we detected constitutive upregulation of several genes contributing to the disease such as Il17f, Il22, and Il23 in vehicle-treated DKO skin relative to single KO or CO (and data not shown)." (PMID 29789551, 2018). "In conclusion, serum levels of TNF-α, IFN-γ, IL-2, IL-6, IL-8, IL-18, IL-22, chemerin, lipocalin-2, resistin, sE-selectin, fibrinogen and C3 were significantly elevated and serum level of adiponectin was significantly decreased in psoriasis patients compared to healthy individuals." (PMID 29416693, 2018). "In addition, our findings suggest that the SDF-1-dependent migration of Lin− CD123+ CD127low cells from the PB to the skin may precede the activation and local production of IL-17 and IL-22 in psoriasis patients." (PMID 28303135, 2017).
psoriasis (continued). "Our findings are supported by previous siRNA knockdown studies that showed targeted inhibition of JAK1 and TYK2 resulted in an almost complete elimination of IL-17, IL-22, and TGFβ signaling functions that could be harnessed therapeutically to treat patients with psoriasis pathogenesis and cancer." (PMID 29164058, 2017). "Although IL-22 has anti-inflammatory properties, such as preserving epithelial integrity and promoting wound healing responses, it is also expressed in many chronic inflammatory conditions, such as psoriasis and rheumatoid arthritis, and its upregulation often correlates with disease activity." (PMID 28558005, 2017). "Remarkably, expression of IL-22 and particularly IL-17 by the Lin− CD123low population in the skin of psoriasis patients strongly suggests that this population may contribute to the immunopathological hallmarks of a skin disease such as psoriasis." (PMID 28303135, 2017). "Finally, mice that artificially overexpress IL-22 develop psoriasis-like spontaneous lesions." (PMID 27148267, 2016). "Given the convincing evidence for a direct contribution of IL-23 to psoriasis, we concentrated on a reductionist model that relies on intradermal injections of IL-23 alone, in which the dermatitis depends on the subsequent expression of IL-22 and IL-17A (refs 11, 16, 17, 38)." (PMID 27982014, 2016). "In addition to IL-17, IL-22 also plays an important role in the pathogenesis of psoriasis." (PMID 26901187, 2016). "In fact, in a mouse model of imiquimod-induced psoriasis-like inflammation, topical curcumin was demonstrated to improve the skin lesions with an effect comparable to that of clobetasol and to significantly decrease the cutaneous levels of IL-17A, IL-17F, IL-22, IL-1β, IL-6, and TNF-α mRNA." (PMID 26090395, 2015). "Furthermore, IL-22 strongly induces hyperplasia of in vitro reconstituted human epidermis and may be responsible for the acanthosis typically found in psoriasis." (PMID 26090395, 2015). "In summary, this study revel the feedback loop between IL22 and miR-197 and suggests that miR-197 acts as a modulator, linking between the immune system and KC, which may play a substantial role in the pathogenesis of psoriasis." (PMID 25208211, 2014). "Moreover, transgenic mice expressing IL-22 develop psoriasis-like symptoms." (PMID 23382730, 2013). "Thus IL-22 is a potential target in the therapy of psoriasis." (PMID 23531535, 2013). "While IL-22 has been implicated in psoriasis, a benign hyperproliferative keratinocyte disease that shares gene expression patterns with SCC, mounting evidence suggests that IL-22 may also be implicated in malignant processes." (PMID 23667456, 2013). "Therefore, the induction by IL-22 of K17 expression suggests that a “Th17/IL-22/K17 autoimmune loop” exists in psoriasis: K17 induces the activation and proliferation of T cells in psoriasis; T cells then produce IL-22, which can induce the expression of K17, forming an interacting cycle." (PMID 22808266, 2012). "Hence, IL-22 could be centrally involved in the pathogenesis of psoriasis, a disease characterized by very high levels of numerous chemokines and antimicrobial peptides." (PMID 20847812, 2010). "We found that IL-10 is significantly associated with psoriasis GWAS whereas IL-22 is not." (PMID 21152006, 2010). "Here, a digital surface-enhanced Raman spectroscopy (SERS) immunoassay has been developed for multiplex detection of IL-17A, IL-22, IL-23 and TNF in punch biopsy skin using psoriasis as a model." (PMID 42124321, 2026). "In psoriasis explants, SHIN1 decreased the expression of Ki67, Keratin 16, and pro-inflammatory cytokines including IL-17A, IL-22, and IFN-γ." (PMID 42103703, 2026). "Elevated IL-17 and IL-22 weakens the BBB by disrupting tight junctions, facilitating immune cell infiltration and sustaining neuroinflammation in chronic skin diseases like psoriasis." (PMID 41393358, 2026).
psoriasis (continued). "For instance, in psoriasis, Th1 cells can secrete tumor necrosis factor (TNF)-α, while Th22 cells secrete interleukin (IL)-22, and Th17 cells secrete IL-17, IL-22, and TNF-α." (PMID 40862458, 2025). "In studies on psoriasis, UVB irradiation suppressed the epidermal expression of IL-17, IL-22, and IFN-γ and rapidly depleted the intraepidermal T-cells." (PMID 40243413, 2025). "To further explore the inflammatory cytokines regulated by TP treatment, we extracted serum from the mice and analyzed the expression of inflammatory genes, such as IL-17A, IL-22, IL-23, TNF-α, and IL-6, which were closely related to psoriasis pathogenesis." (PMID 40365308, 2025). "The shared involvement of IL-17, IL-22, and TNF-α in psoriasis and AA underscores a common inflammatory pathway, though the therapeutic responses vary." (PMID 39859462, 2025). "Recent evidence has clearly demonstrated that these epidermal CD8+ T-cells are the actual producers of the psoriasis signature cytokines IL-17, IL-22, and TNF-α that convey the skin changes characteristic of psoriasis." (PMID 40243413, 2025). "The impact of IL-17A on psoriasis is modest by itself, but its significant influence in the disease’s development and progression is enhanced through synergy with TNF-α, IL-22, and IFN-γ." (PMID 40303401, 2025). "Primary outcomes were Psoriasis Area and Severity Index (PASI), Dermatology Life Quality Index (DLQI), physician global assessment (PGA), interleukins (IL-6, IL-17, IL-23, IL-22), and adverse events." (PMID 41459063, 2025). "STAT1 is another important regulator: its downregulation promotes STAT3 activation and IL-22 production, whereas activation of STAT1 suppresses skin inflammation in imiquimod-induced psoriasis models." (PMID 40906403, 2025). "Contrarily, after Guselkumab withdrawal, increases in serum levels of IL-17A, IL-17F, and IL-22 lagged behind PASI worsening, indicating they are poor predictors of psoriasis flare-ups." (PMID 40699767, 2025). "Increased IL-22 expression in psoriatic skin lesions correlates with the psoriasis area and severity index (PASI), a measure of psoriatic skin severity, suggesting that psoriatic skin lesions depend on IL-22 expression in addition to the IL-23/Th17 axis." (PMID 40861543, 2025). "In addition to IL-22, ILC3-produced IL-17 could be associated with skin pathology in psoriasis." (PMID 41467015, 2025). "Both psoriasis and IBD involve dysregulation of the Th17 immune pathway and overexpression of cytokines such as IL-17 and IL-22, which sustain chronic inflammation in the skin and gastrointestinal tract." (PMID 41153620, 2025). "Cytokines like IL-17A, IL-22, IL-23, and tumor necrosis factor-a (TNF-α) play a role in psoriasis pathogenesis." (PMID 40343294, 2025). "Psoriasis is predominantly mediated by pro-inflammatory cytokines, including TNF-α, IL-17, IL-22, and IFN-γ, secreted by activated T cells." (PMID 40922376, 2025). "At the same time, psoriasis patients produce a significant amount of inflammatory factors, such as IFN−γ (interferon γ), IL-22 (interleukin-22), TNF−α (tumor necrosis factor α) and IL−1β (interleukin-1β)." (PMID 40385577, 2025). "This is the first study to compare the therapeutic potential of intact and cytokine-preconditioned (IL-17, IL-22, and TNF-α) hUCB-MSCs and hUCB-MSC-Exo in a mouse model of IMQ-induced psoriasis-like skin inflammation." (PMID 40906403, 2025). "In turn, hBD-2 in patients with psoriasis or RA increases the production of TNF-α, IFN-γ, IL-10, IL-1β, IL-6, and IL-22." (PMID 40062148, 2025). "As we can see, additional preconditioning of hUCB-MSCs with proinflammatory cytokines (IL-17, IL-22, and TNF-α), which are elevated in patients with psoriasis, promotes higher expression of IL-6 protein." (PMID 40906403, 2025). "To this end, we first examined the expression of IL1B, IL17, IL22 and IFNG, all well-known cytokines involved in the pathogenesis of psoriasis, in the scRNAseq dataset." (PMID 40746860, 2025).